CLEC2B (C-type lectin domain family 2 member B)
Description:
Membrane-bound protein expressed on myeloid cells which acts as a ligand to stimulate the activating receptor NKp80/KLRF1, expressed on the surface of natural killer (NK) cells. In turn, stimulates NK-cell cytotoxicity and cytokine production leading to the cytolysis of malignant CLEC2B-expressing myeloid cells.
Synonyms: AICL; CLECSF2; IFNRG1; HP10085
Tractability: Antibody: UniProt places it where antibodies can reach, with high confidence; its Gene Ontology location is reachable by antibodies, with high confidence; UniProt predicts a signal peptide or a membrane-spanning region. PROTAC: UniProt records ubiquitination sites on it; ubiquitination databases record sites on it.
Gene: Protein-coding gene on chromosome 12 (9,852,369 to 9,870,635, reverse strand). Ensembl gene ENSG00000110852.
Subcellular location: Cell membrane; Golgi apparatus membrane
Pathways (Reactome):
Immune System: Immunoregulatory interactions between a Lymphoid and a non-Lymphoid cell
Gene Ontology:
Molecular function: identical protein binding; protein binding; receptor ligand activity; carbohydrate binding; natural killer cell lectin-like receptor binding
Biological process: NK T cell activation; T cell receptor signaling pathway
Cellular component: Golgi membrane; plasma membrane
Genetic constraint (gnomAD): Loss-of-function variants: 0 observed, 1.87 expected, observed/expected ratio (o/e) 0, 90% interval 0 to 1.4. That is too few expected variants to judge how well the gene tolerates losing a copy. Missense variants: 27 observed, 37.8 expected, observed/expected ratio (o/e) 0.71, 90% interval 0.52 to 0.99. Synonymous variants: 11 observed, 12.8 expected, observed/expected ratio (o/e) 0.86, 90% interval 0.54 to 1.42.
Homologues: Orthologues: chimpanzee CLEC2B (100% identical), macaque CLEC2B (90% identical), dog CLEC2B (61% identical), pig CLEC2B (45% identical), zebrafish si:ch211-170d8.8 (26% identical), zebrafish si:ch211-193e13.5 (25% identical), Caenorhabditis elegans clec-146 (22% identical), Drosophila melanogaster rgn (21% identical), zebrafish si:dkey-26c10.5 (19% identical), Caenorhabditis elegans clec-196 (16% identical). Paralogues in human: CLEC2D (42% identical), CLEC2A (32% identical), CD69 (30% identical), CLEC12B (28% identical), CLEC2L (26% identical), KLRG1 (26% identical), KLRF1 (25% identical), CLEC7A (24% identical), KLRC1 (24% identical), KLRG2 (24% identical), CLEC9A (23% identical), KLRB1 (23% identical), and 11 more.
Diseases named in the same sentence as CLEC2B in open-access papers:
CLEC2B is named in the same sentence as 21 diseases in open-access papers, as found by Europe PMC text mining. Sharing a sentence is not in itself a finding about the gene and the disease. The quoted sentences say what the papers report.
melanoma (4 papers, 2020 to 2023). A malignant, usually aggressive tumor composed of atypical, neoplastic melanocytes. "In previous studies, CLEC2B has been identified as a marker for a variety of cancers, including clear cell renal cell carcinoma, melanoma, and pancreatic adenocarcinoma." (PMID 36030279, 2022). "CLEC2B and IFI27PDE4B were used as independent risk factors of melanoma metastasis." (PMID 37762054, 2023). "In addition, CLEC2B is a prognostic biomarker in cancer, including endometrial cancer and melanoma." (PMID 37246213, 2023). "We constructed a 6-gene signature (IQCE, RFX6, GPAA1, BAHCC1, CLEC2B, and AGAP2) as a novel prognostic marker for predicting the survival of melanoma patients." (PMID 32462000, 2020). "In addition, immunohistochemistry analysis demonstrated that IQCE, RFX6, GPAA1, BAHCC1, CLEC2B, and AGAP2 were highly expressed in melanoma tissues compared with normal tissue." (PMID 32462000, 2020). "In order to verify whether IQCE, RFX6, GPAA1, BAHCC1, CLEC2B, and AGAP2 were highly expressed in melanoma tissues as predicted, we experimentally confirmed this by qRT-PCR and immunohistochemical staining using melanoma tissues extracted from 10 patients." (PMID 32462000, 2020).
clear cell renal cell carcinoma (2 papers, 2020 to 2022). "CLEC2B is a marker of clear cell renal cell carcinoma and other tumors." (PMID 32462000, 2020).
ovarian carcinoma (2 papers, 2018 to 2021). A malignant neoplasm originating from the surface ovarian epithelium. "Particularly, we examined if ANPEP (from EC2), CASP14 and CLEC2B (from EC3), CADM3 and NRBP2 (from EC4), and SPC25, ESCO2, and GTSE1 (from EC5) are responsible for ovarian cancer cell proliferation by the cell viability assay." (PMID 34459128, 2021). "Additionally, our study identified a number of novel markers, such as CASP14, CLEC2B, CADM3, NRBP2, SPC25, ESCO2, and GTSE1, which are upregulated in a cluster‐specific manner and critical for ovarian cancer cell proliferation and migration." (PMID 34459128, 2021).
psoriatic arthritis (2 papers, 2022 to 2023). Joint inflammation associated with psoriasis. "More importantly, as a key gene exclusively linked to ferroptosis regulators in psoriatic arthritis, CLEC2B is differentially expressed in a variety of cancers and is closely associated with immune cell infiltration as well as immune checkpoints." (PMID 36030279, 2022). "This is the first time that CLEC2B has been found to be associated with the development of psoriatic arthritis through natural killer cells." (PMID 36030279, 2022). "Based on this, we infer that CLEC2B may be the most likely gene associated with ferroptosis in psoriatic arthritis, which is linked to a high risk of cancer." (PMID 36030279, 2022). "As a result, we propose that CLEC2B, via ferroptosis regulators, may be a bridge gene for disease progression and a high cancer risk in psoriatic arthritis." (PMID 36030279, 2022). "Given that, CLEC2B was considered as a key gene which bridges the gap between the development of psoriatic arthritis and cancer through ferroptosis." (PMID 36030279, 2022).
breast carcinoma (1 paper, 2020). "CLEC2B, HLA-E, IL15, and VIM all appear in the 4 subtypes at the same time, which may mean that they play a more general role in different subtypes of breast cancer." (PMID 33304391, 2020).
co-infection (1 paper, 2025). "In result 3.4, CLEC2B/C/D-KLRB1 signaling was significantly present in both the HC and mono-infection groups but completely disappeared in co-infection group." (PMID 41394852, 2025).
pancreatic cancer (1 paper, 2023). "Among them, CASP4, TOB1, and CLEC2B were associated with poorer prognosis in pancreatic cancer patients, while FYN showed a correlation with better prognosis." (PMID 37753069, 2023). "CASP4, FYN, TOB1, and CLEC2B exhibited close associations with infiltrating Treg cells in pancreatic cancer, suggesting their involvement in Treg cell functions." (PMID 37753069, 2023).
vitiligo (1 paper, 2012). Generalized well circumscribed patches of leukoderma that are generally distributed over symmetric body locations and is due to autoimmune destruction of melanocytes. "CLEC2B gene, which encodes an activating ligand of the NK cells, is also found in our study to be up-regulated in vitiligo skin." (PMID 23251420, 2012). "Since CLEC2B can be up-regulated by toll-like receptor stimulation, and topical imiquimod (an activator of the toll-like receptors) has been shown to induce vitiligo, we speculate that the increased expression of CLEC2B is a reflection of the activated innate immune system in vitiligo skin." (PMID 23251420, 2012).
tumor (13 papers, 2015 to 2025). "Cell communication analysis also revealed specific interactions between CD1C+ cDC2 cells and T/NK cells in multi‐primary tumours, highlighting the involvement of CLEC2B/CLEC2C molecules and KLRB1 as ligands in this interaction." (PMID 39601163, 2024). "Among 38 subtypes of immune cells, we found that the CLEC2B expression significantly correlated with most subtypes in different tumor types." (PMID 36030279, 2022). "For paired tumor and normal tissues in TCGA pan-cancer, CLEC2B was expressed at high levels in 4 tumors and low levels in 7 tumors." (PMID 36030279, 2022). "Six characteristic genes (IQCE, RFX6, GPAA1, BAHCC1, CLEC2B, and AGAP2) were selected by random forest feature selection, many of which have been reported to be associated with tumor progression." (PMID 32462000, 2020). "We used the coxph function of the R package to build a Cox proportional hazards regression model to analyze the relationship between CLEC2B expression and prognosis in each tumor, and statistical tests were performed using Logrank test to obtain prognostic significance." (PMID 36030279, 2022). "CLEC2B belongs to C-type lectins which facilitate the tumor metastasis in many cancers." (PMID 31772156, 2019). "The scores of immunomodulatory interactions manifested a downgrade in tumor tissues, largely influenced by CLEC2D, CLEC2C, CLEC2B, and KLRB1." (PMID 40723292, 2025). "Subsequently, we applied the COX regression model and conducted ROC analysis to identify the final set of tumor-related genes (TRGs), which included CASP4, FYN, TOB1, and CLEC2B." (PMID 37753069, 2023). "The CLEC network primarily comprised CLEC2C/CLEC2B/CLEC2D-KLRB1 pairs and was specifically expressed in non-tumor cells." (PMID 38065972, 2023). "Furthermore, IFNG+ T cells activate cytotoxic T cells through CLEC2B/C/D-KLRB1 signaling, enhancing their tumor-killing capacity." (PMID 41203637, 2025).
cancer (4 papers, 2022 to 2024). A tumor composed of atypical neoplastic, often pleomorphic cells that invade other tissues. "Furthermore, CLEC2B was discovered differentially expressed in a variety of cancers and is closely associated with immune cell infiltration as well as immune checkpoints." (PMID 36030279, 2022). "Studies have also suggested that CLEC2B activation in platelets plays a crucial role in development, inflammation, and cancer." (PMID 37753069, 2023). "After investigating the pan-cancer section of ENCORI, an online tool, CISD1 was discovered to be highly linked to CLEC2B, CLEC12B and CSTA in a variety of cancer types." (PMID 36030279, 2022). "Among them, CISD1 was also found to be closely linked to CLEC12B, CLEC2B and CSTA in a variety of cancers, with CLEC2B being involved in the largest number of cancer types." (PMID 36030279, 2022). "The findings revealed an exclusive correlation between CISD1 (ferroptosis regulator) and CLEC2B (hub gene) in PsA group as well as multiple cancer types." (PMID 36030279, 2022). "Similar to the findings of prior studies, this study found vital functions for CLEC2B in numerous cancers, including changes in expression, correlation with prognosis, infiltration of multiple immune cells and even immune checkpoints in multiple cancer types." (PMID 36030279, 2022). "Our findings revealed that CLEC2B was correlated with most immunoinhibitors and immunostimulators in multiple cancer types, suggesting that CLEC2B could collectively influence the prognosis of multiple cancers through immunosurveillance." (PMID 36030279, 2022).
immune dysfunction (1 paper, 2025). "This makes CLEC2B a potential marker for immune dysfunction and defective placental vascularization." (PMID 41403942, 2025).
CLEC2B also shares sentences with these, for which no sentence is quoted: viral infections (2 papers); acute myocardial infarction (1); artery occlusion (1); atherosclerosis (1); cholangiocarcinoma (1); endometrial cancer (1); infection (1); myeloid leukemia (1); osteoarthritis (1); urticaria (1).